CCL24 (C-C motif chemokine ligand 24)
Diseases named in the same sentence as CCL24 in open-access papers (continued):
Sharing a sentence is not in itself a finding about the gene and the disease.
chronic asthma (1 paper, 2013). An asthma that is characterized by the development of persistent airway inflammation and recurrent attacks of breathlessness and wheezing, which vary in severity and frequency. "In the first part of this study, we demonstrated that induction of an experimental acute exacerbation of chronic asthma is associated with striking upregulation of the expression by AM of arginase-1, FIZZ1, eotaxin-2/CCL24, and Ym1, all of which are markers characteristic of alternative activation." (PMID 23936781, 2013).
colitis (1 paper, 2022). Inflammation of the colon. "Importantly, while, CCL24 was initially described as an eosinophil chemoattractant trough the receptor CCR3, experiments in rodents suggested it was not involved in eosinophil infiltration during colitis." (PMID 36311796, 2022).
colorectal neoplasm (1 paper, 2017). A benign or malignant neoplasm that affects the colon or rectum. "Meanwhile, CCL24 has been extensively studied in colorectal tumors these years." (PMID 28042950, 2017).
diabetes (1 paper, 2021). "Here, we used inflammatory antibody microarrays to screen serum from patients with diabetes and early DN, and we found that CCL24 expression was increased significantly in patients with DN." (PMID 34221188, 2021).
heart failure (1 paper, 2023). Inability of the heart to pump blood at an adequate rate to meet tissue metabolic requirements. "Because CCL24 is mainly secreted by M2 macrophages, we found that heart failure patients had significantly elevated levels of M2 macrophages and cardiac CCL24 expression compared with healthy donor individuals." (PMID 36131165, 2023). "CCL24/CCR3 axis plays a crucial role in the pathological development of cardiac remodeling during heart failure induced by Ang II." (PMID 36131165, 2023). "Then, we revealed that the level of plasma CCL24 in heart failure is higher than healthy volunteers." (PMID 36131165, 2023). "And inhibition of CCL24 can be a potential therapeutic target in heart failure in mice of Ang II infusion." (PMID 36131165, 2023). "These bioinformatics results are highly consistent with our molecular biology results; therefore, we can verify the participation of the CCL24/CCR3 axis in the pathology of heart failure and cardiac fibrosis." (PMID 36131165, 2023). "Therapeutic targeting of CCL24 hindered adverse cardiac reconstruction and pathology; therefore, providing an appealing novel approach for curing heart failure and cardiac fibrosis." (PMID 36131165, 2023). "We demonstrated firstly that CCL24 /CCR3 axis is involved in cardiac remodeling during the pathology of heart failure." (PMID 36131165, 2023). "We revealed that the expression of cardiac CCL24 and plasma CCL24 were higher in heart failure patients compared with normal donators, and blocking CCL24 in mice alleviated Ang II–induced electrical remodeling and heart failure." (PMID 36131165, 2023). "We aimed to investigate the effect and mechanism of pleiotropic chemokine CCL24 in heart failure." (PMID 36131165, 2023). "Cardiac M2 macrophages, CCL24 and circulation CCL24 increased in heart failure patients." (PMID 36131165, 2023). "Therefore, we speculated that CCL24/CCR3 is involved in cardiac remodeling during heart failure, and we planned to investigate the role and mechanism of the CCL24/CCR3 axis in Ang II–induced heart failure." (PMID 36131165, 2023). "First of all, we just only verify the role of the CCL24/CCR3 axis in heart failure with monoclonal blocking antibody; however, we do not verify it with transgenic mice." (PMID 36131165, 2023).
Hypercholesterolemia (1 paper, 2023). An increased concentration of cholesterol in the blood. "They found that LYVE1+ macrophages, which express high levels of CCL24, expand under hypercholesterolemia in Apoe−/− mice and promote the conversion of vascular smooth muscle cells to osteoblasts/chondrocytes in a CCL24-dependent manner." (PMID 37180791, 2023).
hypertrophic cardiomyopathy (1 paper, 2023). A condition in which the myocardium is hypertrophied without an obvious cause. "In CCL24 Ab group RNA-seq found that it was related to immune responses and hypertrophic cardiomyopathy, CytoF revealed M2 macrophages and monocytes decreased obviously." (PMID 36131165, 2023). "GSEA (Gene Set Enrichment Analysis) found that the CCL24 Ab group was related to immune response, inflammatory response, innate immune response, and cellular response to LPS, and the CCL24 Ab group was negatively related to cardiac muscle contraction and hypertrophic cardiomyopathy." (PMID 36131165, 2023). "Furthermore, according to our bulk RNA-seq result, CCL24/CCR3 axis was negatively related to muscle contraction, cardiac muscle contraction, heart contraction, and hypertrophic cardiomyopathy and immune and inflammatory response." (PMID 36131165, 2023).
ischemic stroke (1 paper, 2024). A stroke disorder caused by obstruction of blood flow to the brain, due to thrombotic (local blood clot formation) or embolic (due to a blood clot or other material traveling from another site) event. "CCL24 was reported to be significantly increased after symptomatic intracranial hemorrhage following ischemic stroke, a rare but severe complication of intravenous thrombolysis, suggesting its role as a potential biomarker for hemorrhagic transformation." (PMID 38332938, 2024). "We found that the change in gene expression of CCR3 and ligands (CCL5, CCL11, and CCL24) is positively correlated with infarct volume in our transient rat model of ischemic stroke." (PMID 38332938, 2024). "We measured the change in expression of CCR3 and its ligands (CCL5, CCL11, and CCL24) in the venous blood prior to and after occlusion in our transient rat model of ischemic stroke." (PMID 38332938, 2024).
liver cirrhosis (1 paper, 2017). "In univariate analysis, γ-GT, tumor number, tumor size, microvascular invasion, TNM stage, BCLC stage and CCL24 level were associated with OS, whereas, γ-GT, liver cirrhosis, tumor number, tumor size, microvascular invasion, TNM stage, BCLC stage and CCL24 level were associated with TTR." (PMID 28042950, 2017). "In multivariate analysis, γ-GT, tumor size, TNM stage and CCL24 level were associated with OS, whereas, γ-GT, liver cirrhosis, tumor number, microvascular invasion, BCLC stage and CCL24 level were associated with TTR." (PMID 28042950, 2017). "Further investigations revealed the prognostic value of CCL24 expression in HCCs with AFP > 20 ng/mL, without liver cirrhosis, within a solitary tumor, microvascular invasion, and TNM stage II+III in the HCC patient subgroups." (PMID 28042950, 2017).
meningioma (1 paper, 2019). A generally slow growing tumor attached to the dura mater. "In our study, we detected slightly higher serum levels of CCL24 in Grade I meningioma patients in comparison to the control subjects." (PMID 31649887, 2019). "Compared to the control group, Grade I meningioma patients showed increased serum levels of amphiregulin (AREG), CCL24, CD69, prolactin, EGF, HB-EGF, caspase-3, and decreased levels of VEGFD, TGF-α, E-Selectin, BAFF, IL-12, CCL9, and GH." (PMID 31649887, 2019).
metastatic colorectal cancer (1 paper, 2025). "High CCL24 expression has also been observed in tumor tissues of patients with metastatic colorectal cancer (mCRC)." (PMID 40397411, 2025).
metastatic tumor (1 paper, 2025). "Three patients had high expression of CCL24 in their tumors and the remaining three had low expression of CCL24 in their metastatic tumor tissues." (PMID 40397411, 2025).
Myocardial fibrosis (1 paper, 2023). "We revealed that CCL24 plays a crucial role in Ang II–induced myocardial fibrosis and structural remodeling." (PMID 36131165, 2023). "According to a previous study, the level of CCL24 in old mice’s cardiac tissues was higher than in young mice; then, we found that the myocardial fibrosis in old mice’s hearts was even worse than in young mice." (PMID 36131165, 2023).
non-small cell lung carcinoma (1 paper, 2023). A group of at least three distinct histological types of lung cancer, including non-small cell squamous cell carcinoma, adenocarcinoma, and large cell carcinoma. "CCL24 was a risk factor for prostate cancer, and CCL27 was a risk factor for non-small cell lung cancer." (PMID 38075694, 2023).
onchocerciasis (1 paper, 2013). Onchocerciasis is a form of filariasis, caused by the parasitic worm Onchocerca volvulus, transmitted by the black fly. "Following treatment of onchocerciasis patients with ivermectin, Eotaxin-2/CCL24 and MCP-4/CCL13 enhanced suggesting that these chemokines facilitated clearance of O. volvulus microfilariae by monocytes and eosinophil granulocytes." (PMID 23855879, 2013).
prostate carcinoma (1 paper, 2023). A carcinoma that arises from epithelial cells of the prostate gland. "Cochrane’s Q test did not provide evidence of heterogeneity between CCL18 (p = 0.767), CCL19 (p = 0.093), CCL24 (p = 0.935), CXCL17 (p = 0.210) and prostate cancer." (PMID 38075694, 2023).
Pruritus (1 paper, 2024). Pruritus is an itch or a sensation that makes a person want to scratch. "Similarly, both GRP and, to a lesser extent, CCL24 (eotaxin-2) were found in higher concentrations in MF patients with current pruritus as compared to those without." (PMID 39068637, 2024). "However, we observed a similar trend in SS, with higher levels of IL-31, GRP, and CCL24 in those with current pruritus compared to those without." (PMID 39068637, 2024). "Furthermore, we observed elevated levels of CCL24 (eotaxin-2) in pruritic MF patients as compared to those without pruritus, with a weak but significant correlation with itch intensity." (PMID 39068637, 2024). "A comparison of MF patients with and without pruritus revealed higher levels of IL-31, substance P, GRP, and CCL24 in the former." (PMID 39068637, 2024).
RSV bronchiolitis (1 paper, 2025). "In contrast, plasma CCL24 levels were significantly lower in the RSV bronchiolitis group compared to the control group [133.02 (121.46, 332.92) pg/mL vs. 232.94 (140.59, 469.12) pg/mL; P < 0.01]." (PMID 41360931, 2025).
schistosomiasis (1 paper, 2023). An infectious disease caused by parasitic trematodes of the genus Schistosoma that colonize human blood vessels and release eggs that can cause granulomatous reactions leading to acute (swimmer's itch or acute schistosomiasis syndrome) or chronic disease. "Serum levels of CCL24 were significantly higher in ST2−/− mice compared with WT mice between the 8th and 10th weeks of S. mansoni infection; however, in the chronic phase of schistosomiasis, the serum levels of CCL24 were similar in both mouse strains." (PMID 37373379, 2023).
Schistosomiasis japonica (1 paper, 2020). Schistosomiasis caused by Schistosoma japonicum. "Our data showed that after S. japonicum infection, a large number of eosinophils around granulomas in the livers, spleens, and large intestines of mice with advanced schistosomiasis japonica, as expected, the levels of CCL11 and CCL24 were increased in the liver, spleen, or large intestine." (PMID 32231658, 2020).
steatosis (1 paper, 2015). Increased lipid within the cytoplasm of cells. "Previous studies have reported that eotaxin-2/CCL24, IL-1α, IL-12, and TNF-α, respectively, are the important mediators in the steatosis model." (PMID 25799095, 2015). "In this study, eotaxin-2/CCL24, IL-1α, IL-12, and TNF-α production in mice treated with CCl4 was increased compared with that in control mice, suggesting these cytokines and chemokines play a critical role in CCl4-induced steatosis." (PMID 25799095, 2015).
tumor (50 papers, 2013 to 2026). "The upregulated CCL24 in CRC liver metastasis promotes the formation of inflammatory tumor‐associated fibroblast subsets and induces resistance to bevacizumab therapy." (PMID 40397411, 2025). "CCL24 promotes the formation of inflammatory tumor‐associated fibroblast subsets in the CRC liver metastasis microenvironment and induces resistance to bevacizumab therapy." (PMID 40397411, 2025). "Through transcriptomic sequencing analysis of tumours in WT and ApoE−/− mice, we observed that ApoE deficiency resulted in decreased expression levels of the immunologically relevant genes CCL24, CD74, and CX3CR1." (PMID 40662483, 2025). "CCL21, CCL22, and CCL24 are genes encoded by C–C motif chemokine ligands, which are components of intercellular communication and essential in the functioning of the tumor microenvironment." (PMID 37537613, 2023). "Previous studies showed that chemokine (C–C motif) ligand 24 (CCL24) is expressed in some tumor cells, and CCL24 was associated with cancer progression." (PMID 35578660, 2022). "Univariate and multivariate analyses demonstrated that CCL24 expression in tumor cells served as an independent risk factor for both OS and TTR (P = 0.013, HR = 1.783; P = 0.012, HR = 1.666)." (PMID 28042950, 2017). "Therefore, CCL24 may be involved in tumor progression, although the underlying mechanism remains unclear." (PMID 40397411, 2025). "Inhibition or knockout of CCL24 suppressed AOM/DSS-induced colorectal tumorigenesis in mice, reduced the population of tumor-associated macrophages (TAMs), and increased CD8+ T cell numbers." (PMID 41694595, 2026). "In the study cohort, CCL24 expression in the tumor tissues was higher than that in the corresponding adjacent normal tissues." (PMID 40397411, 2025). "The tube formation assay on HUVECs showed that tumor cells containing CCL24 promoted vessel formation." (PMID 40397411, 2025). "After eliminating the interference of endogenous CCL24 chemokines, overexpression of CCL24 in LOVO cells significantly promoted tumor progression and increased tumor burden in the mCRC animal model." (PMID 40397411, 2025). "For example, in the absence of CD200R, tumor-associated myeloid cells (TAMCs) increase the expression of C-C motif chemokine ligand 24 (CCL24), resulting in enhanced eosinophil infiltration and thereby boosting anti-tumor capabilities." (PMID 40034598, 2025). "Using next‐generation sequencing, we found that in tumor tissues with high CCL24 expression, iCAF markers (IL1A, IL1B, IL6, CXCL1, and CXCL5) were significantly highly expressed, indicating high infiltration of iCAFs in the TME." (PMID 40397411, 2025). "After analyzing the clinical specimens via IHC staining, patients with CRC receiving Bev treatment had high CCL24 expression in tumor tissues." (PMID 40397411, 2025). "Based on these results, a primary cell‐derived extracellular vehicle delivery system is designed for the simultaneous delivery of siRNAs targeting CCL24 in the tumor microenvironment (TME)." (PMID 40397411, 2025). "Here, it is found that the expression of CCL24 is significantly upregulated in tumor tissues at the CRC liver metastasis site." (PMID 40397411, 2025). "For instance, we detected an increase in CCL2, CCL22, and CCL24 levels in all tumor spheroids upon monocyte addition." (PMID 34451433, 2021). "In tumor bearing mice CCL24, CD163 and MMP7 were upregulated after therapy and IL24 and Odc1 were downregulated (p > 0.05)." (PMID 34944584, 2021). "This analysis revealed that CCL24 was the most consistently altered factor among all the cytokines in all independent tumor clones." (PMID 32051393, 2020). "In fact, IL-33 promoted eosinophil migration to the tumor indirectly, via induction of the chemokines CCL5 and CCL24/eotaxin-2 by tumor cells themselves." (PMID 31717819, 2019).
tumor (continued). "Upon further analysis of the clinical characteristics of 315 HCC patients, we found high CCL24 expression was significantly correlated with increased age (p=0.009), positive HBsAg (p=0.026), and larger tumor size (p=0.036)." (PMID 28042950, 2017). "In this study, we used an antibiotic-treated (Abt) mouse model and firstly demonstrated that commensal microbiota maintained alveolar macrophages with a low level of CCL24 production, which was necessary for them to generate anti-tumor activity." (PMID 28785009, 2017). "In this study, we firstly demonstrated that commensal microbiota maintained alveolar macrophages with a low level of CCL24 production to generate anti-metastatic tumor activity." (PMID 28785009, 2017). "In conclusion, we demonstrated the ability of commensal bacteria to maintain alveolar macrophages with a low level of CCL24 production, which was necessary for the normal anti-tumor response in the lung." (PMID 28785009, 2017). "In summary, by using Abt mouse model we demonstrated the ability of commensal bacteria to maintain alveolar macrophages with a low level of CCL24 production, which was necessary for the normal anti-tumor response in the lung." (PMID 28785009, 2017). "On one hand, we mainly focused on the efficiency of CCL24 in tumor cells and ignored the whole immune microenvironment of HCC." (PMID 28042950, 2017). "CCL24 was injected to nude mice to monitor tumor formation and pulmonary metastasis; qRT-PCR, western blot and Immunohistochemistry were used to explore potential mechanism." (PMID 28042950, 2017). "We knocked down the HCT116 cell line with high endogenous expression and the results showed that knocking down CCL24 in HCT116 cells resulted in a significant reduction in the tumor burden of mCRC animal model mice, while enhancing the therapeutic effect of Bev treatment in mice." (PMID 40397411, 2025). "Overexpression of CCL24 in LOVO cells resulted in a significant increase in tumor burden and decrease in survival rate of the mCRC animal model, including an increase in tumor size, liver weight, and estimated metastasis site, and decrease in OS (HR = 4.64, P = 0.002)." (PMID 40397411, 2025). "In addition, CCL24 is significantly upregulated in tumor tissues from bevacizumab‐resistant patients." (PMID 40397411, 2025). "In addition, CCL24 expression is elevated in some tumour tissues and plasma and can be used as a potential therapeutic marker for tumour diagnosis." (PMID 37076508, 2023). "In addition, CCL24 can combine with CCR3 to recruit eosinophils and tumor-associated macrophages, and immune function is limited when CCR3/CCL24 is suppressed." (PMID 36976996, 2023). "Moreover, the expressions of CXCL14, CCL20, CCL24, and CCL26 were associated with tumor purity and infiltration of CD4+ T cell, CD8+ T cell, B cell, macrophage, dendritic cell, and neutrophil in PCa." (PMID 36275733, 2022). "According to the results, DM may promote cancer progression through inducing the abnormal expression of tumor-related genes; we suggest that the level of CCL24 should be evaluated in cancer patients complicated with DM." (PMID 35578660, 2022). "CCL24 was increased in treated tumor bearing mice and was reduced in cured mice." (PMID 34944584, 2021). "Furthermore, the tumor-promoting behavior of alveolar macrophages was dependent on CCL24 in the Abt mice." (PMID 28785009, 2017). "Furthermore, CCL24 neutralization also resulted in smaller tumor size and less number of tumor foci in the lungs of the Abt mice on day 17 after the challenge." (PMID 28785009, 2017). "Thus, the role of macrophage-derived CCL24, particularly in tumor development, is worthy of attention." (PMID 28785009, 2017). "Until now, there has been limited research on the role of CCL24 in host tumor immune responses." (PMID 28785009, 2017). "Interestingly, tumor tissues derived from SKA-/SKCXCR2 induced greater CCL24, compared to cultured cells from SKA/SKCXCR2." (PMID 27723802, 2016).